RXFP2 (relaxin family peptide receptor 2)
Description:
Receptor for relaxin. The activity of this receptor is mediated by G proteins leading to stimulation of adenylate cyclase and an increase of cAMP. May also be a receptor for Leydig insulin-like peptide (INSL3).
Synonyms: GPR106; GREAT; LGR8; INSL3R; RXFPR2; LGR8.1
Tractability: Small molecule: it belongs to a druggable protein family. Antibody: its Gene Ontology location is reachable by antibodies, with high confidence; UniProt places it where antibodies can reach, with medium confidence; UniProt predicts a signal peptide or a membrane-spanning region. PROTAC: a small molecule that binds it is known. Other modalities: a drug acting on it is in phase 2 or 3 trials.
Target class: Relaxin receptor; Relaxin-like peptide receptor (family A GPCR); Family A G protein-coupled receptor; Peptide receptor (family A GPCR); Membrane receptor
Gene: Protein-coding gene on chromosome 13 (31,739,526 to 31,803,389, forward strand). Ensembl gene ENSG00000133105.
Subcellular location: Cell membrane
Pathways (Reactome):
Signal Transduction: G alpha (s) signalling events; Relaxin receptors
Gene Ontology:
Molecular function: G protein-coupled peptide receptor activity; G protein-coupled receptor activity; peptide hormone binding; protein-hormone receptor activity
Biological process: adenylate cyclase-activating G protein-coupled receptor signaling pathway; hormone-mediated signaling pathway; adenylate cyclase-inhibiting G protein-coupled receptor signaling pathway; G protein-coupled receptor signaling pathway; negative regulation of apoptotic process; negative regulation of cell population proliferation; oocyte maturation; signal transduction
Cellular component: plasma membrane; membrane
Genetic constraint (gnomAD): Loss-of-function variants: 35 observed, 42.38 expected, observed/expected ratio (o/e) 0.83, 90% interval 0.63 to 1.1. The upper end of that interval is the gene's LOEUF score, 1.1, which puts it in group 4 of 6, group 1 being the genes least tolerant of losing a copy. Missense variants: 463 observed, 571.51 expected, observed/expected ratio (o/e) 0.81, 90% interval 0.75 to 0.88. Synonymous variants: 206 observed, 200.72 expected, observed/expected ratio (o/e) 1.03, 90% interval 0.92 to 1.15.
Homologues: Orthologues: chimpanzee RXFP2 (99% identical), macaque RXFP2 (96% identical), dog RXFP2 (89% identical), guinea pig RXFP2 (86% identical), rabbit RXFP2 (85% identical), pig RXFP2 (85% identical), rat Rxfp2 (81% identical), mouse Rxfp2 (81% identical), tropical clawed frog rxfp2 (68% identical), zebrafish rxfp2b (56% identical), zebrafish rxfp2a (55% identical). Paralogues in human: RXFP1 (52% identical), TLR3 (17% identical), TLR7 (17% identical), TLR8 (15% identical), TLR2 (15% identical), TLR1 (15% identical), TLR5 (14% identical), TLR6 (14% identical), TLR10 (14% identical), TLR4 (13% identical), IGFALS (13% identical), LRRC32 (13% identical), and 10 more.
Diseases named in the same sentence as RXFP2 in open-access papers:
RXFP2 is named in the same sentence as 31 diseases in open-access papers, as found by Europe PMC text mining. Sharing a sentence is not in itself a finding about the gene and the disease. The quoted sentences say what the papers report.
cryptorchidism (24 papers, 2007 to 2025). The failure of one or both testes of a male fetus to descend from the abdomen into the scrotum during the late part of pregnancy. "This INSL3/RXFP2 pairing is essential for the proper descent of the testicles during development in mammals, and loss of rxfp2a results in cryptorchidism in mice." (PMID 40344089, 2025). "Mutations in the INSL3/RXFP2 genes are associated with cryptorchidism or undescended testis, a reproductive birth defect characterized by impaired fertility due to spermatogenic maturation arrest." (PMID 40794697, 2025). "Mutations or polymorphisms in INSL3 and RXFP2 genes (encoding the INSL3 receptor) are associated with cryptorchidism." (PMID 41595460, 2025). "Experimental studies have shown that cryptorchidism is associated with genetic abnormalities occurring in INSL3/RXFP2." (PMID 38407794, 2024). "Mutations in the RXFP2 gene have been associated with human cryptorchidism, indicating its involvement in sex-related phenotypes." (PMID 39227755, 2024). "Overall, the phenotypes of cryptorchid males with mutations in the INSL3 and RXFP2 genes vary significantly from unilateral cryptorchidism in the first year of life to persistent bilateral cryptorchidism." (PMID 38407794, 2024). "Several population studies, however, have indicated an association between heterozygous mutation in either INSL3 or RXFP2 and the incidence of cryptorchidism (usually unilateral)." (PMID 35464060, 2022). "Analysis of the history of cryptorchidism patients found that about 22.7% of patients had a family history of cryptorchidism; recessive mutation of RXFP2 (c.1496G>A." (PMID 34828386, 2021). "Mutations inINSL3 and LGR8 (RXFP2) have been reported inpopulations of patients with cryptorchidism." (PMID 26650439, 2015). "The disruption of RXFP2 or INSL3 causes cryptorchidism and infertility." (PMID 39272405, 2024). "Poor cell surface expression and failure to bind INSL3 or respond to the ligand with cAMP signaling was observed in the functional analysis of the variant protein, concluding that recessive endowment of variants of the RXFP2 gene can lead to genetic familial cryptorchidism." (PMID 37189986, 2023). "The optimization of compound dosage, vehicle, delivery route, target exposure, as well as further testing in various models of cryptorchidism and diseases associated with bone loss are required to establish the pharmacological utility of identified RXFP2 agonists." (PMID 36333465, 2022). "Although decreased blood INSL3 levels and mutations in Insl3/RXFP2 genes have been linked to a small number of human cryptorchidism cases, functions of the INSL3-RXFP2 system in species other than mice are largely unknown." (PMID 21138583, 2010). "The interaction of Insl3 with Rxfp2 controls the differentiation of gubernaculum, the caudal genitoinguinal ligament critical for testicular descent, and deletion of Insl3 or Rxfp2 causes cryptorchidism." (PMID 17623071, 2007). "Disruption of the Rxfp2 gene causes cryptorchidism, which affects spermatogenesis." (PMID 17623071, 2007). "Our findings reveal how evolutionary changes in the INSL3/RXFP2 pathway contribute to natural cryptorchidism in mammals and provide insights for investigating reproductive health and cancer resistance in cryptorchid species." (PMID 41219539, 2025). "This study examines how evolutionary relaxation and functional change of INSL3 and RXFP2 relate to natural cryptorchidism in mammals." (PMID 41219539, 2025). "Recently, mutation studies in human patients with bilateral cryptorchidism and male infertility reported bi-allelic loss-of-function (LoF) variants in INSL3 and RXFP2, while carriers of the heterozygous variant remain phenotypically unaffected." (PMID 40794697, 2025). "Genetic alterations of INSL3 and its receptor RXFP2 were correlated not only with cryptorchidism but also with azoospermia and crypto-/azoospermia." (PMID 41595460, 2025).
cryptorchidism (continued). "Similar bilateral cryptorchidism was also achieved in the male offspring of pregnant rats treated with a specific RXFP2 competitive antagonist." (PMID 35464060, 2022). "Another recent study reported two possible genetic biomarkers associated with canine cryptorchidism; hypomethylation of a single CpG site in the 5’-flanking region of INSL3, and a SNP in the 5’ flanking region of RXFP2." (PMID 35617214, 2022). "Whilst its function in the adult mammal is less clear, genetic studies in humans and mice show that loss of function of the genes for either the hormone or its receptor, called RXFP2 (relaxin-family peptide receptor 2), leads to cryptorchidism." (PMID 27031644, 2016). "To study the consequences of an aberrant testicular environment in cryptorchidism we used a mouse model with a deletion of Rxfp2 gene resulting in a high intra-abdominal testicular position." (PMID 24098584, 2013). "INSL3 and its receptor relaxin family peptide receptor 2 (RXFP2) play important roles in descent of the testes during the transabdominal phase, and single-nucleotide polymorphisms in the INSL3 and RXFP2 genes are risk factors for cryptorchidism." (PMID 33256838, 2020). "Knockout experiments in mice clearly show independent requirements for INSL3/RXFP2 and androgens in testicular descent; nevertheless causative mutations in INSL3, RXFP2, AR (androgen receptor) or the Leydig cell regulator NR5A1 (steroidogenic factor-1), are rare in cases of cryptorchidism." (PMID 30083133, 2018). "Studies in mice lacking RXFP2 had confirmed this receptor as INSL3’s sole mediator in vivo, with similar gene mutations identified in cryptorchid patients." (PMID 41219539, 2025). "Even if the etiology of cryptorchidism in male boys is unknown, it is hypothesized that it is determined by multiple factors, and is most likely due to the altered signaling of INSL3/RXFP2." (PMID 37189986, 2023). "Mutation analysis of INSL3/RXFP2 genes has been suggested in patients with a history of cryptorchidism, and mutations in the NR5A1 gene are emerging as a significant cause of primary spermatogenic impairment associated or not with cryptorchidism." (PMID 32486230, 2020). "However, it seems that Rxfp2 is not essential for spermatogenesis, because if the cryptorchidism that results from the lack of Rxfp2 is surgically corrected at birth, sperm maturation appears normal." (PMID 17623071, 2007).
osteoporosis (6 papers, 2011 to 2024). A condition of reduced bone mass, with decreased cortical thickness and a decrease in the number and size of the trabeculae of cancellous bone (but normal chemical composition), resulting in increased fracture incidence. "RXFP2 has been found in humans and mice to be positively correlated with testosterone levels in blood, while mutations in RXFP2 have been found to be associated with osteoporosis and testicular descent in mice and humans." (PMID 31681413, 2019). "Young men with mutations in the gene for the INSL3 receptor (Relaxin family peptide 2, RXFP2) are at risk of reduced bone mass and osteoporosis." (PMID 22216350, 2011). "Firstly, and strongly supported by the present findings, INSL3 is known to promote bone metabolism, with genetic defects in the receptor RXFP2 in mice and humans both leading to osteoporosis and osteopenia, and with clear effects on bone cells in culture." (PMID 36425465, 2022). "For example, the RXFP2 gene is not only related to testicular dysplasia in humans and mice but also plays important roles in bone metabolism and osteoporosis." (PMID 31771503, 2019).
arterial hypertension (2 papers, 2022 to 2024). "Experimentally, we validated the variant to gene analysis and show that RXFP2 gene expression is increased in adrenal gland of men with hypertension." (PMID 38851835, 2024). "The directionality derived from colocalization indicates that genetic factors associated with higher risk of rHTN are also associated with higher adrenal RXFP2 expression, which is consistent with the known biological role of the adrenal gland in hypertension." (PMID 38851835, 2024). "Whether adrenal RXFP2 also causes hypertension through PLC/PKC-medicated increases in aldosterone or through catecholamine production remains to be elucidated." (PMID 38851835, 2024). "This study shows that adrenal gland gene expression of RXFP2 is increased in men with hypertension and the RXFP2 natural ligand, INSL3, increases adrenal steroidogenesis and corticosteroid secretion in human adrenal cells." (PMID 38851835, 2024). "The discovery that CASZ1 and RXFP2 are involved in the development of PA provides new pathophysiological insight and opens perspectives for the diagnosis and treatment of arterial hypertension." (PMID 36057693, 2022).
male infertility (2 papers, 2015 to 2018). The inability of the male to effect fertilization of an ovum after a specified period of unprotected intercourse. "Both genes are necessary for gubernacular function, as knockout of RXFP2 or INSL3 in mice results in the absence of the gubernaculum and no testicular descent, which in turn leads to spermatogenesis defects and male infertility." (PMID 29953435, 2018).
resistant hypertension (2 papers, 2022 to 2024). "Herein we conduct genome-wide association studies to identify new potential causes of resistant hypertension and report that RXFP2 is associated with rHTN in men." (PMID 38851835, 2024). "Recently, SNPs near CASZ1, LSP1 and RXFP2 have been associated with resistant hypertension in a genome-wide association study of 14,756 patients from Iceland, the UK Biobank and eMERGE33." (PMID 36057693, 2022). "Furthermore, it provides pathophysiological explanations for the previously observed association of CASZ1 and RXFP2 with blood pressure and resistant hypertension." (PMID 36057693, 2022).
thyroid cancer (2 papers, 2015 to 2022). "RXFP2 is also a receptor for INSL3 (insulin-like peptide 3) and has been implicated with tumor-promoting activity in thyroid cancer." (PMID 25857299, 2015). "INSL3 could promote tumor growth and angiogenesis in nude mice model of thyroid cancer in a manner that appeared to be related to the action of RXFP2 and the secretion of S100A4 and (pro-) cathepsin-L." (PMID 35178089, 2022).
Atrophy (1 paper, 2018). Any weakening or degeneration, especially through lack of use. "The possible role of INSL3/RXFP2 pathway on skeletal muscle was assessed in vivo through the application of an atrophy model on Rxfp2−/− mice." (PMID 30323788, 2018).
blood pressure (1 paper, 2024). "Sex-stratified analysis in both 23andMe and UK Biobank show the association only in men indicating that RXFP2 may play a role in the higher blood pressure in men." (PMID 38851835, 2024).
ciliopathy (1 paper, 2022). A genetic disorder of the cellular cilia or the cilia anchoring structures, the basal bodies, or of ciliary function. "Eight of the 140 potential ciliopathy genes had predicted secondary interaction with gold standard cilia proteins, Aplnr, Casr, Gcgr, Grm6, Med1(or Mbd4), Mlh1, Rxfp2, and Wdr62.." (PMID 36456625, 2022). "In addition, 7 genes had primary interactions with the 24 directly interacting potential ciliopathy genes and thus had secondary interactions with known cilia proteins: Aplnr, Casr, Gcgr, Grm6, Med1(or Mbd4), Mlh1, and Rxfp2." (PMID 36456625, 2022).
hyperaldosteronism (1 paper, 2024). Overproduction of aldosterone by the adrenal glands, which may lead to hypokalemia and/or hypernatremia. "Phenome-wide significant associations of the GWAS lead SNP with hyperaldosteronism and other hypertension-related diseases further strengthen the hypothesis for a role of RXFP2 in rHTN." (PMID 38851835, 2024).
primary aldosteronism (1 paper, 2024). An endocrine disorder characterized by excessive production of aldosterone by the adrenal glands. "rs1535532 was one of the top eQTLs for RXFP2 in the adrenal gland and the PheWAS with primary aldosteronism was specific to men17." (PMID 38851835, 2024).
Sciatica (1 paper, 2021). Pain in the lower back and hip radiating in the distribution of the sciatic nerve. "AZU1, BPI, TCF7L2, and WFIKKN1 were upregulated in sciatica patients, while ANGPTL4, CRP, EREG, FAM19A4, FGF1, LOC100129216, PLXNB1, RLN1, and RXFP2 were downregulated." (PMID 34925462, 2021).
cancer (5 papers, 2015 to 2025). A tumor composed of atypical neoplastic, often pleomorphic cells that invade other tissues. "Lastly, the discovery of RXFP2’s unique role in cancer, mediated by its interaction with INSL3, opens new avenues for targeted cancer therapies." (PMID 39000413, 2024). "Similarly, we found that BDKRB1/2 and RXFP2/3 in module 3 have high prognostic significance in five cancer types." (PMID 28676692, 2017). "Under the differentially expressed genes we identified several genes previously related to cancer including the up-regulated SSX1, SSX2, RXFP2, RYR2 and the down-regulated CSTA, TSPAN7, NEO1, S100A, SERPINB5 and SEPP1." (PMID 25857299, 2015).
renal diseases (1 paper, 2024). "Overall, we identified RXFP2 activity as a potential new mechanism in rHTN and discovered RXFP2 antagonists for the future interrogation of RXFP2 in cardiovascular and renal diseases." (PMID 38851835, 2024).
RXFP2 also shares sentences with these, for which no sentence is quoted: tumor (3 papers); anorchia (2); autism (1); Azoospermia (1); endocrine disorders (1); endometriosis (1); Hypernatremia (1); hypertension (1); Hypokalemia (1); Infertility (1); neurological disorders (1); Obesity (1); Osteopenia (1); pneumonia (1); prostate carcinoma (1); testis (1); uterine disease (1).